IGFL2 (IGF like family member 2)
Description:
Potential ligand of the IGFLR1 cell membrane receptor.
Synonyms: UNQ645; VPRI645
Tractability: Antibody: UniProt places it where antibodies can reach, with high confidence; UniProt predicts a signal peptide or a membrane-spanning region; its Gene Ontology location is reachable by antibodies, with medium confidence; the Human Protein Atlas places it where antibodies can reach.
Gene: Protein-coding gene on chromosome 19 (46,143,106 to 46,161,298, forward strand). Ensembl gene ENSG00000204866.
Subcellular location: Secreted
Subcellular location (Human Protein Atlas): Nucleoplasm; Plasma membrane; Predicted to be secreted
Gene Ontology:
Molecular function: signaling receptor binding
Cellular component: extracellular region
Genetic constraint (gnomAD): Loss-of-function variants: 6 observed, 13.98 expected, observed/expected ratio (o/e) 0.43, 90% interval 0.23 to 0.85. The upper end of that interval is the gene's LOEUF score, 0.85, which puts it in group 3 of 6, group 1 being the genes least tolerant of losing a copy. Missense variants: 130 observed, 145.54 expected, observed/expected ratio (o/e) 0.89, 90% interval 0.77 to 1.03. Synonymous variants: 54 observed, 57.37 expected, observed/expected ratio (o/e) 0.94, 90% interval 0.75 to 1.18.
Homologues: Orthologues: chimpanzee IGFL2 (92% identical). Paralogues in human: IGFL3 (57% identical), IGFL4 (42% identical), IGFL1 (37% identical).
Diseases named in the same sentence as IGFL2 in open-access papers:
IGFL2 is named in the same sentence as 14 diseases in open-access papers, as found by Europe PMC text mining. Sharing a sentence is not in itself a finding about the gene and the disease. The quoted sentences say what the papers report.
hepatocellular carcinoma (3 papers, 2021 to 2023). A malignant tumor that arises from hepatocytes. "IGFL2 has been identified as a member of 12 marker panel of cancer-associated fibroblasts associated with the progression of hepatocellular carcinoma." (PMID 36895481, 2023). "Similarly, studies have also reported the tumor-promoting role of IGF2BP1, IGF2BP3, IGFBP6 and IGFL2 in several cancers such as hepatocellular carcinoma, pancreatic and prostate cancers." (PMID 34061869, 2021).
psoriasis (2 papers, 2023 to 2025). An autoimmune condition characterized by red, well-delineated plaques with silvery scales that are usually on the extensor surfaces and scalp. "Studies suggests that the expression levels of IGFL2 are diminished in psoriasis compared to healthy control skin." (PMID 40455785, 2025).
abscess (1 paper, 2025). An inflammatory process characterized by the accumulation of pus within a newly formed tissue cavity which is the result of a bacterial, fungal, or parasitic infection or the presence of a foreign body. "IGFL2 and WNK2 showed negatively correlated with abscess count (r = -0.44, p = 0.1; r = -0.43, p = 0.11)." (PMID 40455785, 2025).
pulmonary fibrosis (1 paper, 2022). Chronic progressive interstitial lung disorder characterized by the replacement of the lung tissue by connective tissue, leading to progressive dyspnea, respiratory failure, or right heart failure. "In addition, no other potential markers IGFL2, NECAB1, SCG5 were found to play a role in pulmonary fibrosis." (PMID 36507532, 2022).
tumor (9 papers, 2012 to 2026). "Calculation of correlation of immune-related genes with IGFL2 expression and tumor mutational burden and microsatellite instability." (PMID 37055418, 2023). "After establishing that IGFL2 expression is broadly associated with pan-cancer prognosis, we analyzed whether it influences tumor progression in the tumor microenvironment." (PMID 37055418, 2023). "IGFL2 expression is significantly elevated in tumor tissue and high expression has a worse prognosis in most cancers." (PMID 37055418, 2023). "To explore the influence of IGFL2 on the tumor microenvironment, we analyzed the correlation between TMB and MSI in pan-cancer." (PMID 37055418, 2023). "WT1, COL11A1, FGF5, and IGFL2 were up-regulated in tumor tissues, while GFAP and CD300LG were down-regulated." (PMID 33987034, 2021). "In contrast, IGFL2 expression was higher in normal than tumor tissues of SKCM, TGCT, UCEC, and UCS." (PMID 37055418, 2023). "IGFL2 was up-regulated in the four types of BC in our result, which might contribute to tumor cell growth." (PMID 33987034, 2021). "Analysis of tumor-infiltrating immune cells revealed a negative correlation between IGFL2 and monocytes in several cancers, including ccRCC and pRCC." (PMID 39331921, 2024). "Importantly, we found a population of IGFL2+ KIR3DL2+ tumor cells that was largely absent in nonlesional MF or healthy control skin, which might be crucially involved in the formation of actively inflamed, clinically visible MF lesions." (PMID 34583709, 2021).
cancer (5 papers, 2021 to 2024). A tumor composed of atypical neoplastic, often pleomorphic cells that invade other tissues. "Upregulation of IGFL2 expression is consistently linked to poorer patient prognosis and is associated with the extent of immune cell infiltration in multiple cancer types." (PMID 39331921, 2024). "Upregulation of IGFL2 expression was associated with poor patient prognosis and correlated with the level of immune cell infiltration in several cancers." (PMID 37055418, 2023). "Meanwhile, we analyzed the IGFL2 mutation levels using cBioPortal (TCGA, Pan-Cancer Atlas) and found that the highest mutation levels were found in UCS, over 6%, all of which were gene amplifications." (PMID 37055418, 2023). "In most cancers, IGFL2 methylation is lower and the group with mutations in IGFL2 has a worse prognosis than the normal group." (PMID 37055418, 2023). "In this study, we comprehensively analyzed the effects of IGFL2 expression, prognosis, immunity, methylation, mutation and pathways in pan-cancer." (PMID 37055418, 2023). "Then we analyzed the samples of KIRC, KIRP, and KICH simultaneously to obtain the results of mixed renal carcinoma, which showed that IGFL2 expression was significantly higher in the advanced stage of cancer than in the early clinical stage, and was a risk factor affecting prognosis." (PMID 37055418, 2023). "Insulin-like growth factor like family member 2 (IGFL2) is a gene in the IGFL family, located on chromosome 19, whose role in cancer is unclear, and the aim of this study was to investigate the relevance of IGFL2 expression, prognosis, immunity, and mutation in pan-cancer." (PMID 37055418, 2023). "It is suggested that the mutation of IGFL2 may have influenced the survival rate of cancer." (PMID 37055418, 2023). "the results of COX regression analysis showed that IGFL2 was associated with a variety of tumors, including KIRP, KIRC, BLCA, MESO, PAAD and other cancers." (PMID 37055418, 2023). "In the analysis of DNA methylation, we found that IGFL2 was reduced in methylation in a variety of cancers." (PMID 37055418, 2023). "This study found that IGFL2 expression was positively correlated with most immune cells in most cancers." (PMID 37055418, 2023). "To further investigate the association between IGFL2 and the degree of immune infiltration in different cancers, we investigated the correlation between IGFL2 and immune checkpoint gene expression." (PMID 37055418, 2023). "This suggests that IGFL2 may serve as a prognostic marker, particularly impacting the prognosis of ccRCC as it plays a multifaceted role in cancer development and immune responses." (PMID 39331921, 2024). "IGFL2 may be involved in the development of many types of cancer, influencing the course of cancer with different biological functions." (PMID 37055418, 2023). "After changing the survival index to DFS, the statistically significant cancers were PAAD, KIRP, and in the K-M survival curve analysis, the elevated expression of IGFL2 in PAAD 3.31 (1.33–8.22) and KIRP 2.32 (1.02–5.27) affected the prognosis." (PMID 37055418, 2023).
IGFL2 also shares sentences with these, for which no sentence is quoted: breast carcinoma (2 papers); Arthritis (1); bladder cancer (1); clear cell renal cell carcinoma (1); gastric cancer (1); head and neck squamous cell carcinoma (1); prostate carcinoma (1); thyroid cancer (1).